CASP8 (caspase 8)
Diseases named in the same sentence as CASP8 in open-access papers (continued):
Sharing a sentence is not in itself a finding about the gene and the disease.
breast carcinoma (continued). "Complementarily, we reported that breast cancer tissues of patients, bearing a homozygous -652 6N Del variant, displayed lowest relative CASP8 expression, which corroborates that this effect is similarly applicable for malignant breast cancer tissue." (PMID 27507139, 2016). "Germline sequence variants in and near the CASP8 gene have been implicated in susceptibility to several different cancer types including breast cancer, melanoma, basal-cell carcinoma (BCC) and chronic lymphocytic leukaemia." (PMID 26740556, 2016). "A number of single nucleotide polymorphisms (SNPs), including one in caspase-8 (CASP8), have been previously associated with risk of developing breast cancer." (PMID 26758508, 2016). "The Breast Cancer Association Consortium (BCAC) has identified 3 SNPs in CASP8, namely rs1045485, rs17468277, and rs1830298, which are associated with breast cancer risk." (PMID 26758508, 2016). "Conclusively, we observed a significant allele-dose dependent association between CASP8 -652 6N Del allele and decreased caspase 8 mRNA expression in primary breast cancer tissue." (PMID 27507139, 2016). "Given the importance of replicating genetic associations, our study, conducted in a well-established, well-characterized prospective cohort contributes important information on the relationship between CASP8 polymorphisms and breast cancer risk." (PMID 26758508, 2016). "An association with an increased risk of developing breast cancer was found in the SNPs localized in the CASP8, TNRC9 and ESR1 genes." (PMID 26770289, 2016). "The aim of this study was to examine potential associations between 12 CASP8 polymorphisms and breast cancer risk, overall and by subtype, using case and control samples nested within the California Teachers Study (CTS)." (PMID 26758508, 2016). "We observed an allele-dose dependent association between CASP8 -652 6N InsDel and caspase 8 mRNA expression in breast cancer tissue, with homozygous deletion carriers showing lowest relative caspase 8 expression (p = 0.0131)." (PMID 27507139, 2016). "While our results should be validated in other cohorts with subtype-specific information, this study contributes to our understanding of CASP8 SNPs and subtype-specific breast cancer risk." (PMID 26758508, 2016). "A recent meta-analysis concluded that CASP8 rs1045485 does reduce the risk of breast cancer in minor allele carriers, at least in Caucasian populations." (PMID 22045194, 2012). "In this context, it is of interest to note that recent studies suggest an important role for a caspase-8 gene polymorphism in the susceptibility to develop ovarian cancer and breast cancer." (PMID 22558117, 2012). "Studies have revealed that the polymorphism in the CASP8 coding region, D302H, was associated with reduced breast cancer risk." (PMID 23554680, 2011). "To date, the only SNP associated with breast cancer risk with genome-wide statistical significance (P < 10-7) coming from candidate gene approaches is CASP8; more equivocal evidence has been reported for SNPs in TGFB1 and ESR1, among others." (PMID 21194473, 2010). "It needs to be determined if the loss of CASP8 and/or maspin expression can be a prognostic marker for Breast Cancer and if it is associated with amplification of MYCN (v-myc myelocytomatosis viral related oncogene), as frequently observed in neuroblastomas." (PMID 20132554, 2010). "An association study using candidate genes recently identified caspase-8 (CASP8) as a low-risk susceptibility gene where the major (H) allele of the D302H polymorphism had a protective effect on the development of breast cancer." (PMID 21037853, 2010). "Using MSP and bisulfite sequence analysis, we have established the relationship between aberrant cytosine methylation and downregulated or loss of CASP8 in breast cancer cells." (PMID 20132554, 2010).
breast carcinoma (continued). "Taken together, the results from MSP confirmed that the loss of CASP8 gene and protein expression in these breast cancer cells resulted from CASP8 promoter methylation." (PMID 20132554, 2010). "In an earlier study, CASP8 D302H variant was reported to be associated with reduced breast cancer risk in a dose-dependent manner; it provided better protection against breast cancer in the homozygous condition." (PMID 21655367, 2008). "For example, SNPs in TOX3 and CASP8 alter the risk for developing breast cancer, and SNPs in FGFR2 and TOX3 are strongly associated with ER-positive breast cancer." (PMID 19094228, 2008). "We establish cis-regulation of CASP8 as a likely causal mechanism underlying melanoma and breast cancer risk at this locus, and given the strong LD between signals, this mechanism may potentially play a role in risk of other associated cancers." (PMID 41542517, 2026). "Besides BRCA1 and BRCA2 mutations that markedly increase breast cancer risk, hundreds of low- and moderate-risk susceptibility variants have been identified, including caspase-8 (rs2293554, rs6723097,), TIMP-2 (rs7501477), and FSCN1 (rs56156320, rs3801004,)." (PMID 39614126, 2025). "Interestingly, we found that CASP8 was nominally associated with a short-term risk for breast cancer providing insights into a potential role of plasma CASP8 levels in breast cancer risk." (PMID 38135714, 2024). "Thus, additional studies designed to provide mechanistic insights into the precise role of CASP8 or related genes and downstream targets in breast cancer risk are needed." (PMID 38135714, 2024). "Notably, among the significantly associated proteins was Caspase 8 (CASP8), which has previously been implicated in breast cancer genetic risk as well as other cancers." (PMID 38135714, 2024). "Furthermore, pyroptosis has been linked to poor patient outcomes, such as in cases where caspase-8/GSDMC-mediated pyroptosis correlates with adverse prognoses in breast cancer patients." (PMID 39221221, 2024). "Given the importance of allelic variations associated with cancers, including breast cancer, this study aimed to investigate the association of CASP8 polymorphisms, haplotypes and diplotypes with breast cancer risk, prognosis, and clinicopathological features in a northeastern population of Iran." (PMID 37016353, 2023). "Furthermore, efforts to identify new variations in fine-mapping and genome-wide association studies have provided evidence of the association of several variants of CASP8 with breast cancer risk." (PMID 37016353, 2023). "Therefore, this study aimed to identify common variations and haplotypes associated with risk and overall survival of breast cancer with respect to underlying susceptibility variants in the CASP8 gene region in a group of the Iranian population." (PMID 37016353, 2023). "Based on the results of this study, which was conducted for the first time in the Northeastern female population of Iran, CASP8 gene polymorphisms, haplotypes, and diplotypes may be used as predictive markers for the risk and prognosis of breast cancer." (PMID 37016353, 2023). "However, rs1045485 in CASP8 was identified in Family 2 as a potential breast cancer risk variant and it was only shared by the proband and the proband’s sister that developed breast cancer at age 51 and 47, respectively." (PMID 35625741, 2022). "Additionally, CASP8 D302H polymorphisms are associated with risk of several types of cancers including breast cancer, brain cancer, and prostate cancer, which indicates its potential utility for stratification of cancer patients." (PMID 33828176, 2021). "Moreover, several studies have reported that multiple cancers carry different Casp8 mutants; for example, Casp8 undergoes somatic frameshift mutations in hepatocellular carcinomas and colorectal carcinomas and point mutations in breast cancer." (PMID 33934451, 2021).
breast carcinoma (continued). "In addition, embelin caused dose-dependent death of breast cancer cells and upregulated cleaved caspase-8, cleaved caspase-9 and cleaved caspase-3 expression." (PMID 34282169, 2021). "However, prognostic relevance of both caspase 8 alleles for breast cancer patients remains to be determined." (PMID 31467295, 2019). "We propose a prognostically favorable role of the CASP8 -652Del and the 302HisHis genotype in primary breast cancer patients and suggest for the first time an association between a polymorphism in an apoptosis-related gene and the immunophenotype of breast cancer." (PMID 31467295, 2019). "A 2011 study evaluated breast cancer risk associations with eight SNPs identified through GWAS and two in the candidate genes caspase 8, apoptosis-related cysteine protease (CASP8), and transforming growth factor, beta-1 (TGFβ1) by immunohistochemistry-defined subtypes." (PMID 31379942, 2019). "Studies conducted about a decade ago showed that the D302H polymorphism in CASP8 (caspase 8, rs1045485) could reduce breast cancer risk." (PMID 30249004, 2018). "While it is known that mutations in BRCA1 and BRCA2 markedly increase one’s risk of developing breast cancer, a number of additional low and moderate-risk susceptibility variants have been identified, including one for caspase-8 (CASP8), an enzyme involved in apoptosis." (PMID 26758508, 2016). "Therefore, further larger (prospective) studies should be initiated to validate clinical utility of these two CASP8 polymorphisms for breast cancer and also to a broad scope of other malignancies." (PMID 27507139, 2016). "This study contributes to our understanding of CASP8 SNPs and breast cancer risk by subtype." (PMID 26758508, 2016). "The CASP8: rs1045494 SNP was previously reported to be associated with breast cancer risk." (PMID 26988918, 2016). "Other CASP8 SNPs have shown to be associated with increased breast cancer risk." (PMID 26758508, 2016). "Because caspase-8 is an important protein involved in receptor-mediated apoptosis whose activity is affected by estrogen, we hypothesized that additional SNPs in CASP8 could be associated with breast cancer risk, perhaps in a subtype-specific manner." (PMID 26758508, 2016). "Similarly, CASP8 302His variant was shown to confer reduced breast cancer susceptibility in an allele-dose dependent manner." (PMID 27507139, 2016). "At first glance, our finding may appear counterintuitive, since the CASP8 -652 InsDel or DelDel genotype has previously been associated with impaired immune surveillance of cancer cells and concomitantly decreased breast cancer susceptibility." (PMID 27507139, 2016). "Various molecular epidemiological studies have suggested that SNPs in caspases may contribute to cancer risk, and a common coding variant in caspase 8 has been associated with breast cancer susceptibility." (PMID 22737080, 2012). "The increased gene expression following demethylation suggested that methylation-dependent transcriptional silencing may cause decreased expression or even total loss of CASP8 and maspin in breast cancer cells." (PMID 20132554, 2010). "Therefore, the objective of the current study was to analyze 785 clinically documented breast cancer patients for the CASP8 -652 6N Ins/Del and CASP8 Asp302His polymorphism and to correlate resulting genotypes with disease-free survival (DFS) and the presence of TILs." (PMID 31467295, 2019). "Collectively, our findings complement previous epidemiological findings, associating CASP8 -652InsDel and CASP8 Asp302His with decreased breast cancer susceptibility and extend clinical relevance of the -652Del variant from predicting breast cancer susceptibility to prognostic stratification." (PMID 31467295, 2019). "HSP reduced the growth of MDA-MB-231 breast cancer cells by inhibiting HER2-tyrosine Kinase (HER2-TK) activity, causing MMP loss, chromatin condensation, and activating of caspase-8 and-3." (PMID 40427522, 2025).
breast carcinoma (continued). "Caspase-8 activation, followed by ensuing activation of downstream caspases is essential for regulating programmed cell death mechanisms that combat breast cancer." (PMID 40612872, 2025). "In the present study, Fulvestrant promoted apoptosis in MCF-7 breast cancer cells by activating caspase-8, a key initiator of the extrinsic apoptotic pathway." (PMID 40649817, 2025). "In contrast, Fulvestrant, a clinically used anti-breast cancer drug, triggered apoptosis via caspase-8 activation, indicating engagement of the extrinsic pathway." (PMID 40649817, 2025). "Apoptosis triggered by DOX was assessed by examining gene and protein expression levels of caspase-3, caspase-8, and caspase-9 in breast cancer cell lines." (PMID 40530298, 2025). "Using the MR combined colocalization method, we identified several plasma proteins associated with breast cancer risk, notably CASP8 and DDX58, which are promising targets for developing screening biomarkers and therapeutic drugs for breast cancer." (PMID 39351539, 2024). "A preliminary study on Iranian breast cancer patients further reported significantly decreased CASP8 expression, which is consistent with our findings." (PMID 39351539, 2024). "Decreased levels of CASP8, DDX58, CPNE1, ULK3, PARK7, and BTN2A1, as well as increased levels of TNFRSF9, TNXB, DNPH1, and TLR1, were linked to an elevated risk of breast cancer." (PMID 39351539, 2024). "It has been demonstrated that Ibrutinib induces breast cancer cell death through apoptosis (caspase-dependent), culminating in the modulation of caspase 3, caspase 8, and PARP1." (PMID 38790974, 2024). "Their findings revealed that Gag-CASP8-VLPs effectively transported CASP8 to breast cancer cells, inducing apoptosis and impeding tumor growth." (PMID 38001342, 2024). "MMPP promoted apoptosis in breast cancer cells via cleavage of caspase-3, caspase-8, and caspase-9 and regulation of Bcl-2 and Bax through the VEGFR2/AKT and PPARγ/PTEN/AKT pathways." (PMID 37942548, 2024). "Apart from that, we found that treatment with rGO and MG-132 or the mix increased apoptosis, necrosis and induction of caspase-8 and caspase-9 activity in both breast cancer cell lines." (PMID 38791473, 2024). "Specifically, genistin has demonstrated its usefulness in the prevention and treatment of breast cancer cells by targeting signaling cascades, inducing apoptotic cell death, activating caspase-8/9, and cleaving poly (ADP-ribose) polymerase." (PMID 39134561, 2024). "IRF1 is an IFN-inducible transcription factor and tumor suppressor that mediates ligand-independent apoptosis via caspase-8 activation in breast cancer cells." (PMID 38660315, 2024). "Chemotherapeutic drugs were found to mediate tumor cell pyroptosis via CASP8 in breast cancer cells." (PMID 38178669, 2024). "In our work, we have shown that selenoesters lead to upregulation of active caspase 8 in breast cancer cells (MCF-7 and MDA-MB-231), which has also been revealed by our previous study." (PMID 39063006, 2024). "Hou’s group found that Caspase-8 can cut GSDMC in hypoxic breast cancer cells, and its expression level was mediated by the PD-L1, following by TNF-α induced pyroptosis." (PMID 37359371, 2023). "A cytometric analysis revealed that compounds 1–3 promoted apoptosis in MCF-7/MDA-MB-231 breast cancer cells via caspase 8/9-related pathways and induced S-phase cell cycle arrest." (PMID 36982886, 2023). "A significant and dose-dependent increase in caspase-8 activation was observed in breast cancer cells pretreated with compounds 1–3." (PMID 36982886, 2023).
breast carcinoma (continued). "LUV-TRAIL loaded with doxorubicin (Dox) in the liposomal lumen, known as LUVDOX-TRAIL, improved cytotoxic potential by enhanced caspase-8 activation in the tumor xenograft model of breast cancer cells." (PMID 37065863, 2023). "A cross-talk between the intrinsic pathway and caspase-8 was already detected for other steroidal AIs studied by our group, namely Exe and its metabolites, in sensitive and in resistant ER+ breast cancer cells." (PMID 36677847, 2023). "BAX inhibition can promote the growth of breast cancer, and progesterone induces the apoptosis of ovarian and endometrial cancer cells by activating caspase-8, calcitriol, and the caspase-9 pathway." (PMID 37263638, 2023). "Recent large meta-analyses and consolidating evidence have highlighted the role of the caspase-8 gene in breast cancer pathogenesis." (PMID 37016353, 2023). "The present study with a carefully selected range of genetic markers across the CASP8 gene region can add more evidence to the literature about the overall role of the gene in breast cancer and improve the information about the genetic basis of the disease." (PMID 37016353, 2023). "Flow cytometric analyses showed that the reference drug (etoposide) statistically significantly increased caspase-8 activation in breast cancer cells only when used at a concentration of 20 μg/mL." (PMID 36982886, 2023). "Fucoidan treatment also resulted in the apoptosis of breast cancer cells due to caspase-8 activation and induced caspase 3 and PARP in human lung cancer cells." (PMID 36135731, 2022). "The activation of FasL and Caspase-8 inhibited the proliferation of breast cancer MDA-MB-231 cells and U937 cells." (PMID 35855902, 2022). "HSPB2 also inhibits the apoptotic pathway by being concentratedly expressed in breast cancer and inhibiting the activation of caspase-8 in breast cancer." (PMID 35154459, 2022). "Dietary flavonoid HSP inhibits HER2 Tyrosine Kinase (HER2-TK) activity, causes MMP loss, chromatin condensation, activates caspase-8 and-3, resulting in cell cycle arrest at the G2 phase, which decreases the SKBR3 in MDA-MB-231 breast cancer cell growth." (PMID 35128104, 2022). "After 24 h incubation of human breast cancer cells with the tested compound, the concentration of Casp-8 was 1.012 ng/mL (1 μM Les-3331) and 1.067 ng/mL (5 μM Les-3331), compared to the untreated control (0.828 ng/mL)." (PMID 35456915, 2022). "Several studies support the role of ω-3 PUFAs in the activation of the extrinsic pathway of apoptosis in promyelocytic leukemia cells (HL-60), as well as in ER+ breast cancer cells, where both studies showed an increase in caspase-8." (PMID 35682855, 2022). "The extrinsic apoptotic initiator caspase-8 and effector caspase-3 protein expressions in breast cancer cells were detected using Western blot." (PMID 34282169, 2021). "The restoration of the expression of caspase-8 has been shown in breast cancer, neuroblastoma, and medulloblastoma using decitabine and azacytidine, nucleoside analogs, which promotes the demethylation of caspase-8 promotor." (PMID 33026575, 2021). "GSDMC is specifically cleaved by caspase-8 at Asp240 and is related to tumor progression in breast cancer due to the induction of chronic inflammation." (PMID 34522213, 2021). "Insertion of full-length SINE-VNTR-Alu retrotransposons (SVT) into intron 8 of the caspase 8 gene (CASP8) is associated with an increased risk of basal cell carcinoma and breast cancer, but reduces the risk of prostate cancer." (PMID 34769514, 2021). "This solution was also enriched in genes known to be associated with breast cancer susceptibility (BLM, CASP8, CASP10, DNAJC1, FGFR2, MRPS30, and SLC4A7, P-value = 3 × 10−4)." (PMID 33735170, 2021).